GFAP (glial fibrillary acidic protein)
Diseases named in the same sentence as GFAP in open-access papers (continued):
Sharing a sentence is not in itself a finding about the gene and the disease.
myelitis (continued). "Autoimmune glial fibrillary acidic protein (GFAP) astrocytopathy is a recently identified disorder characterized by a phenotype of isolated meningoencephalitis or combined with myelitis or optic nerve involvement." (PMID 40581835, 2025). "The clinical features of GFAP/AQP4-IgG double-positive myelitis include urinary retention and sensory disturbances." (PMID 39975853, 2024). "Overall, 14 and 24 patients with GFAP-IgG-and MOG-IgG-associated myelitis, respectively, were retrospectively screened and included in the study." (PMID 38020648, 2023). "Second, the specificity was low when only serum GFAP-IgG was positive, and 3 of 14 GFAP-IgG myelitis cases were only serum positive; however, all cases had characteristic clinical syndromes, and other diseases were reasonably excluded." (PMID 38020648, 2023). "Demographic and clinical characteristics of patients with GFAP-IgG and MOG-IgG-associated myelitis [n (%)]." (PMID 38020648, 2023). "This study retrospectively compared the clinical features, CSF and imaging features, and overlapping antibodies in 14 and 24 patients with GFAP-IgG-and MOG-IgG-associated myelitis, respectively." (PMID 38020648, 2023). "This study provides clinical, CSF, and MRI evidence for recognizing and differentiating GFAP-IgG-and MOG-IgG-associated myelitis." (PMID 38020648, 2023). "Influenza-like prodromal symptoms and bowel/bladder dysfunction are common features in GFAP-IgG myelitis, while numbness and weakness followed by tonic spasms, frequent NMOSD symptoms, are rare." (PMID 32455910, 2020). "In GFAP-IgG myelitis, spinal cord central canal, punctate or leptomeningeal enhancement was typical." (PMID 30568655, 2018). "GFAP antibody-related diseases: May present as myelitis (in approximately 50% of cases), with more frequent involvement of the thoracic spinal cord and less frequent involvement of the lumbar spinal cord." (PMID 40933045, 2025). "Additionally, GFAP-IgG myelitis exhibits distinct spinal cord lesions, often longitudinally extensive, centrally located, and showing subtle imaging features compared to AQP4-IgG lesions." (PMID 39328614, 2024). "CSF findings of GFAP-IgG and MOG-IgG-associated myelitis [n (%)]." (PMID 38020648, 2023). "Therefore, this study retrospectively analyzed and compared the clinical features of GFAP-IgG-and MOG-IgG-associated myelitis to better understand the clinical diagnosis and management processes." (PMID 38020648, 2023). "MRI characteristics of GFAP-IgG and MOG-IgG-associated myelitis [n (%)]." (PMID 38020648, 2023). "The question arises as to whether it is the occurrence of extra-optic nerve disease – such as myelitis – that is the factor determining the higher GFAP levels in NMO." (PMID 21876753, 2011). "However, a relapse in the form of optic neuritis was found to result in markedly lower levels of cerebrospinal GFAP (median 6.1; range 1.1–56.1) than myelitis (median 593.9; range 1.2–47,843.3 ng/mL)." (PMID 21876753, 2011). "Glial fibrillary acidic protein (GFAP) antibody-associated astrocytopathy is a recently described inflammatory condition presenting as meningoencephalitis with various possible signs of CNS involvement, including movement disorders, seizures, brainstem attacks, and myelitis." (PMID 37958968, 2023). "Furthermore, this cycle might be involved in Glial fibrillary acidic protein (GFAP) astrocytopathy, an autoimmune astrocytopathy characterized by fever, headache, encephalopathy (ataxia, delirium, tremor, seizures, or psychiatric symptoms), and myelitis." (PMID 35064896, 2023). "A study comparing GFAP-IgG and AQP4-IgG related myelitis found that 20% of AQP4-IgG related myelitis patients experienced INVH as prodromal symptoms, while GFAP-IgG related myelitis patients did not." (PMID 39949796, 2025). "Spinal cord involvement in GFAP astrocytopathy is commonly observed as part of meningoencephalomyelitis or encephalomyelitis syndrome (42%), rather than as isolated myelitis (5%)." (PMID 39449321, 2024).
myelitis (continued). "Although the clinical spectrum of the disease is broad and heterogenous, GFAP astrocytopathy most commonly presents as meningoencephalitis with or without myelitis." (PMID 39449321, 2024). "None of our 14 patients with GFAP-IgG myelitis had spinal cord lesions confined to gray matter on axial MRI sequences (expressed as the “H sign”)." (PMID 38020648, 2023). "GFAP-IgG lesions have poorly-defined margins and less cord swelling compared to AQP4-IgG myelitis." (PMID 32455910, 2020). "Baseline clinical characteristics of the population reported herein are similar to that of published cases of GFAP, including sex ratio, age at onset and clinical presentation, with meningo-encephalitis with or without myelitis as the main phenotype at onset, and a severe presentation." (PMID 40419703, 2025). "Notably, sensory level and Lhermitte’s phenomenon are usually absent in GFAP-IgG myelitis, which is found in the cervical or thoracic spinal cord, in central location, usually involving at least three vertebral segments." (PMID 32455910, 2020). "In addition, meningoencephalitis, with or without myelitis, in patients with breast cancer may be due to this syndrome, and therefore, the CSF levels of GFAP-IgG should be examined." (PMID 37016352, 2023). "Recently, a novel astrocytic IgG autoantibody targeting glial fibrillary acidic protein (GFAP) has been identified in the CSF and serum of 16 patients with relapsing steroid-responsive meningoencephalitis with or without myelitis and was clinically characterized in a series of 102 patients." (PMID 30364136, 2018).
tauopathy (37 papers, 2015 to 2026). Neurodegenerative disorders involving deposition of abnormal tau protein isoforms (tau proteins) in neurons and glial cells in the brain. "Ablation of C3aR or C3 in mouse models of tauopathy reversed neuronal loss and neurodegeneration, alongside reduced numbers of GFAP-reactive hypertrophied astrocytes being apparent upon C3aR knockout." (PMID 33071951, 2020). "The gene expression profile analysis in a mouse model of tauopathy (rTg4510) which expresses the P301L mutation, revealed upregulation of pro-inflammatory markers such as complement 4B, glial fibrillary acidic protein (GFAP) and osteopontin (Spp1) on treatment with LPS." (PMID 29950970, 2018). "The first principal component (or PC1) loaded positively on p‐tau181 (0.528), p‐tau231 (0.499), GFAP (0.484), and NfL (0.481), suggesting that i reflects a general neurodegeneration and tauopathy‐related biomarker pattern." (PMID 40684252, 2025). "Since activated astrocytes and microglia are pathological hallmarks of tauopathy, we stained for GFAP and IBA1, respectively." (PMID 40697807, 2025). "More recently, new biomarkers are increasingly being validated, including blood-based biomarkers such as pTau 217 and pTau213 for tauopathy, neurofilament light chain (NfL) for neuronal injury, and glial fibrillary acidic protein (GFAP) for neuroinflammation." (PMID 41342674, 2025). "To examine Müller cell gliosis in relation to tauopathy, we assessed GFAP expression in retinal sections at 1, 3 and 8 months of age." (PMID 33762004, 2021). "Alterations in GFAP expression have also been noted in primary tauopathies including PSP, PiD and corticobasal degeneration (CBD)." (PMID 33071951, 2020). "Yet GFAP is redistributed in the cytoplasm of astrocytes containing tau, a feature also found in other tauopathies with tau deposits in astrocytes." (PMID 31907603, 2020). "Our secondary objective was to use the GFAP-luc BLI model to investigate the effectiveness of a new erythropoietin (EPO) based therapeutic agent in the treatment of tauopathies." (PMID 31572168, 2019). "The gliosis response in human CTE has not been well characterized, but the findings by Luo and colleagues show that GFAP was increased near areas of tauopathy." (PMID 26579067, 2015). "Although tauopathy mice at this age did not have increases in Iba1 and GFAP (markers of glia‐associated neuroinflammation) relative to littermate controls, we found that 3TC modestly reduced these proteins in treated transgenic animals." (PMID 36949552, 2023). "In a tauopathy model strain (VH255) expressing normal human tau in C. elegans muscle, tau aggregation caused paralysis that was alleviated to a similar extent by treatment with 1 μM MSR1 or siRNA against ifp-1, the closest nematode homolog of GFAP." (PMID 35890250, 2022). "Together with the phosphorylated-tau results, the increase in FA was associated with increased GFAP immunostaining with no tauopathy, and the FA decrease was associated with increased GFAP immunostaining with tauopathy." (PMID 33716645, 2021). "We conducted systematic and quantitative immunohistochemistry for glial fibrillary acidic protein (GFAP), ionized calcium-binding adaptor molecule 1 (Iba1), amyloid beta, and highly phosphorylated tau (tauopathy)." (PMID 31354934, 2019). "Concordantly, CST reduced expression of CD68, GFAP, IL-6, TNF-α, CXCL1, and CXCL10, extending its known peripheral anti-inflammatory actions 20,38 to the central nervous system and establishing CST as a regulator of neuroimmune homeostasis in Tauopathy." (PMID 41509358, 2026). "Similarly, it has been shown that TREM2 downregulation affects the phenotype of GFAP-positive astrocytes in the APP/PS1 amyloid mouse model and the PS19 model of tauopathy." (PMID 37371067, 2023).
tauopathy (continued). "As increased inflammation is a common feature of tauopathies and was previously observed in TauP301L-AAV mice at 6 months of age, we evaluated GFAP and IBA1 levels, which revealed that both markers are already significantly elevated in TauP301L-AAV animals by 3 months of age." (PMID 30674342, 2019). "We performed triple immunofluorescence studies with antibodies against YKL-40, GFAP and tau in different cases of AD and non-AD tauopathies (n = 40)." (PMID 28599675, 2017). "As expected, colocalization between tau and GFAP was found in non-AD tauopathies reflecting the distinctive glial tau aggregation in these disorders." (PMID 28599675, 2017). "Moreover, many studies have corroborated positive correlation between the GFAP activation with tauopathy independent of Aβ pathology in AD mouse models." (PMID 39913635, 2025). "GFAP seems to predict the presence of Aβ pathology regardless of tauopathy and neurodegeneration, while NfL might be more accurate in discriminating patients who also developed tauopathy, as supported by other authors." (PMID 37723371, 2024).
viral infection (37 papers, 2010 to 2025). "In response to injury of the CNS caused by trauma, neurodegenerative disease, or viral infection, GFAP plays crucial role in the development of reactive astrocytosis." (PMID 33715038, 2021). "Astrogliosis, assessed via glial fibrillary acidic protein (GFAP) immunostaining, was present in both Nef-competent and Nef-deficient EcoHIV-infected mice, reflecting a general response to viral infection in the central nervous system." (PMID 41008347, 2025). "UNOs infected with PeV-A1 Harris or PeV-A3 152037 showed positive dsRNA (indicative of viral infection) in astrocyte (GFAP+) and neuron (MAP2+) rich areas." (PMID 38514653, 2024). "This viral infection leads to ROS production and a decrease in cell viability; the gene expression for GFAP, EAAT1, and GS is downregulated while for NMDAR increased." (PMID 36989308, 2023). "Since also microglia and astrocytes can up-regulate Fas or FasL expression in response to viral infection or stress, we assessed the expression of Fas and FasL on astrocytes (GFAP+) and microglia cells (CD45low+/CD192-/IBA-1+)." (PMID 34526992, 2021). "By 2 weeks after viral infection, compared to MG infected with control GFAP-GFP AAVs, we found that many MG infected with GFAP-Math5-Brn3b-GFP AAVs changed their morphology, lost MG processes and migrated into the GCL." (PMID 34671605, 2021). "GFAP astrocytopathy is accompanied by neoplasms, but the relationship between virus infection and GFAP astrocytopathy is unclear." (PMID 30568655, 2018). "SAFV infected brains showed apoptosis in similar regions as viral infections, and colocalisation with both GFAP and NeuN positive cells were observed." (PMID 27887630, 2016). "We next examined if viral infection is associated with abnormal expression of structural proteins such as doublecortin (DCX) and GFAP." (PMID 21249143, 2011). "Using viral infection-mediated cell-specific introduction of GFAP expression, we showed that these neurons are generated by GFAP-expressing NSCs in the SVZ and migrate radially into the damaged striatum, where they differentiate into mature neurons." (PMID 24710140, 2011). "The exact pathogenic mechanisms, as well as the role of anti-GFAP antibodies, remain unclear; however, it seems that neuroinflammation is mediated by specific CD8+ T-cells and that neoplasms or viral infections can act as the initial trigger." (PMID 39449321, 2024). "Viral infections could activate the immune system through molecular mimicry leading to anti-GFAP antibody production, activation of GFAP-specific CD8+ T-cells, blood–brain barrier disruption, and cellular cytotoxicity leading to target cell apoptosis." (PMID 39449321, 2024). "Virus (AAV8-GFAP-hM3Dq-mCherry), which contained the hM3Dq (Gq) Designer Receptors Exclusively Activated by Designer Drugs (DREADDs) under the astrocyte GFAP promoter and the mCherry tag to localize viral infection, were stereotaxic injected into the primary somatosensory cortex." (PMID 32704144, 2020). "In contrast, in NeuroD1-treated areas, GFAP-labeled astrocytes were always detected in the vicinity of NeuroD1-converted neurons at 2 months, 6 months, or 1 year after viral infection, and less reactive in morphology compared to the control group (NeuroD1-mCherry columns, green signal)." (PMID 33224952, 2020). "RPE65-positive RPE cells and GFAP-positive glial cells were the main targets of viral infection." (PMID 31291924, 2019). "The relationship between virus infection and GFAP astrocytopathy is unclear." (PMID 30568655, 2018). "In addition to nestin expression, the detection of GFAP staining could be related to reactive astrocytes which are well-known as the result of cellular stress following viral infection thereby favoring tumor aggressiveness." (PMID 38553638, 2024).
viral infection (continued). "Interestingly, if mixed glial cultures were grown for 10 days post-virus exposure, the percentage of GFAP+ cells expressing Env was much higher for all virus groups, suggesting that resistance to amphotropic virus infection wanes with time in culture and/or cell-to-cell spread." (PMID 31736699, 2019). "Certain viral infections, such as Epstein-Barr virus (EBV), are known to induce the expression of both GFAP and AQP4 antibodies." (PMID 40688088, 2025). "Since astrocytes play an important role in brain response to viral infections, such as SARS-CoV-2, and inflammation, GFAP can be an important tool to predict astrocytic and CNS damage and neural injury." (PMID 37996731, 2024). "Cre signal was detected clearly in the GFAP+ astrocytes in the control group (GFAP::Cre and FLEX-mCherry) at 2 weeks, 2 months, and 6 months after viral infection (left side)." (PMID 33224952, 2020). "Validating these findings on primary astrocytes, VSV-NLENY1 fluorescent virus infection showed profound infection by expressing YFP and viral p24 protein in GFAP-positive astrocytes." (PMID 25188302, 2014). "Viral infections targeted the midbrain, and the infected efficiency was confirmed by co-label immunofluorescence of enhanced green fluorescent protein (EGFP) with dopaminergic neuron marker (TH), astrocytes marker (GFAP), and microglia marker (IBA-1)." (PMID 40038816, 2025). "Autoimmune GFAP autocytopathy and RESLES are both related to viral infection." (PMID 37190624, 2023). "We first injected the control AAV9 GFAP::GFP viruses into the cortex of Rhesus Macaque monkey (monkey ID #04339) and found that the majority of GFP-infected cells were GFAP+ astrocytes at 28 days post viral infection (dpi), as expected." (PMID 33224952, 2020). "The majority of patients in our study had other neuronal surface antibodies or viral infections, implying that GFAP antibodies might be a non-specific witness of inflammation." (PMID 37205100, 2023). "It is possible that reactivation of the memory T cells, by another injury or perhaps by other neuroinflammatory stimulus, such as bacterial or viral infections, might re-open the BBB and expose the memory immune cells to self-antigens, such as GFAP, UCH-L1 or MBP." (PMID 28124982, 2017).